CTLA4 (cytotoxic T-lymphocyte associated protein 4)
Diseases named in the same sentence as CTLA4 in open-access papers (continued):
Sharing a sentence is not in itself a finding about the gene and the disease.
autoimmune disease (continued). "In the last few years, several genetic SNPs in CTLA-4 and its ligand have been recognized and demonstrated to influence the intensity of T cell-mediated immunity, resulting in various autoimmune diseases, and even the occurrence of post-transplant allograft rejection." (PMID 25013611, 2011). "Data from the current study extend that of previous work identifying that CTLA-4, the IL2_21 region, 6q23 (TNFAIP3), SH2B3, PRKCQ, MMEL1 and now TAGAP are susceptibility loci that are common to the three autoimmune diseases examined in the current study: T1D, CeD and RA." (PMID 20854658, 2010). "Our results lead to the conclusion that genetic variation in CTLA4 does not play an important role in PF susceptibility and that the effect of variations in this gene differs among autoimmune diseases." (PMID 21637411, 2010). "In this study, a strong association was found between the CTLA-4 +49A allele and CD but not with UC, suggesting that the genetic factors for CD are distinct from those of autoimmune diseases." (PMID 19568552, 2009). "CD is not a true autoimmune disease, and has different associations at the CTLA-4 exon 1 +49 G>A from all other autoimmune disorders." (PMID 19568552, 2009). "A G→A nucleotide exchange at position +6230 (also addressed as CT60; according to alternate numbering located at position +6253 relative to the start codon) in the 3′-untranslated region of the human CTLA-4 gene has been found to support protection from several autoimmune diseases." (PMID 19609446, 2009). "Indeed, the known T1D susceptibility loci follow this observation: while both CTLA4 and PTPN22 loci are associated with several autoimmune diseases, the insulin VNTR locus is likely to be T1D-specific rather than a general autoimmune locus." (PMID 16519819, 2006). "A role of CTLA-4 in the pathogenesis in T1D and other autoimmune diseases has been well documented." (PMID 16259622, 2005). "The association of the CTLA-4 gene with several autoimmune diseases such as T1D, Addison's disease, multiple sclerosis, myasthenia gravis and all clinical outcomes of AITD, can also explain the general contribution of CTLA-4 to autoimmunity." (PMID 15762980, 2005). "CTLA-4 has been reported to be an important negative regulator of autoimmune diseases." (PMID 16259622, 2005). "Therefore, CTLA‐4 has a role in preventing autoimmune diseases by regulating immune tolerance." (PMID 38485815, 2024). "However, unlike CTLA-4 knockout mice, which show fatal autoimmune disease, LAG-3-deficient mice do not show signs of autoimmune disease." (PMID 38732104, 2024). "Polymorphisms in genes involved in other autoimmune disorders, including cytotoxic T-lymphocyte associated protein 4 (CTLA-4) and protein tyrosine phosphatase non-receptor type 22 (PTPN22) among others, have been identified as additional risk factors for APS-2." (PMID 36980146, 2023). "Interestingly, another study showed a higher level of CTLA-4 in FOXP3- T cells from patients with SLE compared to other autoimmune diseases and healthy controls, but their study indicated that the FOXP3- T cells in SLE patients were unable to control activation and proliferation of effector T cells." (PMID 37497212, 2023). "The CTLA-4 pathway induces co-stimulatory signals during T-cell activation, providing additional control mechanisms that prevent inappropriate and hazardous T-cell activation that could lead to autoimmune disease pathogenesis." (PMID 36835433, 2023). "The lack of negative immunosuppressive signals from CTLA-4 in the body may cause a decrease in the threshold of lymphocyte activation, leading to the development of autoimmune diseases." (PMID 36133806, 2022). "Considering that abatacept (exogenous CTLA4) is a drug for the treatment of autoimmune diseases, ipilimumab (anti-CTLA4) is an antitumor drug, and OX40 inhibitor is used for treating autoimmune diseases, it is speculated that the OX40 agonist receptor may also have antitumor activity." (PMID 36042469, 2022).
autoimmune disease (continued). "Therefore, the CTLA4 pathway regulates the balance between autoreactive T cells and Treg, and the decrease of CTLA4 expression or function may lead to the occurrence of autoimmune diseases." (PMID 35494032, 2022). "Interestingly, CTLA4 and PDCD1 polymorphisms are associated with autoimmune disorders." (PMID 34898551, 2021). "However, elimination of CTLA-4 may result in the breakdown of immune tolerance and the development of autoimmune diseases." (PMID 34298735, 2021). "As CD28 is the primary driver of Treg proliferation and CTLA-4 functions as the main brake, it implied that although the function of Helios− Tregs was unstable and decreased in autoimmune disease status, they might have more immunosuppressive function compared to Helios+ Tregs." (PMID 34054801, 2021). "However, in autoimmune diseases, the superior affinity of CTLA4 for its ligands led to the use of a CTLA4-immunoglobulin fusion protein (CTLA4-Ig) as an inhibitor of immune responses in vivo; the rationale being that it would bind to CD80 and CD86 and block their interaction with CD28." (PMID 26942414, 2017). "Interestingly, this meta-analysis showed that other loci different from CTLA-4 previously found to be associated with common autoimmune diseases were not statistically significantly associated with GPA in this study." (PMID 25452756, 2014). "Among the CTLA-4 gene polymorphisms, two polymorphisms including CTLA4 60G/A (rs3087243) in the 3’-UTR, and CTLA4 -1661A/G (rs4553808) in promoter region were widely studied and have been reported to be associated with susceptibility to inflammatory diseases, autoimmune diseases and cancers." (PMID 24376736, 2013). "Unlike CTLA-4-deficient mice, PD-1 deficiency leads to autoimmune disorders later in life." (PMID 22997525, 2012). "Our findings may reconcile the apparent discrepancy between reports of elevated levels of sCTLA-4 in plasma from patients with autoimmune disease and the report of decreased levels of the sCTLA-4 transcript among individuals with the CT60 allele of the CTLA-4 gene." (PMID 19772653, 2009). "Cytotoxic T lymphocyte-associated antigen-4 (CTLA-4) plays a critical role in downregulation of antigen-activated immune response and polymorphisms at the CTLA-4 gene have been shown to be associated with several autoimmune diseases including type-1 diabetes (T1D)." (PMID 16259622, 2005). "A polymorphism (Thr17Ala) within the N-terminal signal peptide of CTLA-4 correlates with incomplete CTLA-4 glycosylation and processing at the ER, leading to lower cell surface expression and autoimmune disorders." (PMID 41031910, 2025). "The discovery of immune inhibitory mechanisms, such as CTLA-4, PD-1, and anti PDL-1, lead to a revolutionary understanding of cancer immune evasion, as well as autoimmune diseases." (PMID 40710197, 2025). "This balance between the CTLA-4, CD28, and B7 proteins ensures that T cells can fight infections and cancer while preventing excessive or harmful immune responses, such as autoimmune diseases." (PMID 41155258, 2025). "Our results thus show that NBEAL2 is involved in the regulation of CTLA-4 expression in conventional T cells and provide a rationale for considering CTLA-4-immunoglobulin therapy in patients with GPS and autoimmune disease." (PMID 37349339, 2023). "Patients with autoimmune diseases (e.g., RA, SLE, MS, and T1D) have lower levels of CTLA-4 mRNA and protein in their PBMC, spleen, and lymph nodes than healthy subjects." (PMID 37497212, 2023). "CTLA-4 negatively regulates T cell activation in various ways, and regulating CTLA-4 function is a promising strategy for immunotherapy of autoimmune diseases such as rheumatoid arthritis." (PMID 37304306, 2023). "The coordination of CTLA-4 and CD28 maintains the balance of T-cell immunity in the body, especially after infection and the onset and progression of autoimmune disease." (PMID 37497212, 2023).
autoimmune disease (continued). "Thus, patients with secondary ITP have an underlying autoimmune disease, and the polymorphisms found in the CTLA4 promoter could be related to the underlying autoimmune disease, and not necessarily to the development of ITP." (PMID 35459882, 2022). "Interestingly, they found that several treatments, in particular fingolimod, can induce the expression of CTLA-4 and that its higher expression or function could contribute to reducing the responses of autoreactive T cells and to inhibiting autoimmune diseases, such as MS." (PMID 35893056, 2022). "IRs, including CTLA4, PD1, LAG3, TIM3, TIGIT, and CD96, play a certain role in the pathogenesis of autoimmune diseases." (PMID 35769669, 2022). "Treg cells directly or indirectly inhibit immune response and antibody production by expressing cellular receptors such as CTLA-4 or secreting cytokines such as TGF-β, IL-10, and IL-35, and are the therapeutic target of autoimmune diseases." (PMID 35983038, 2022). "This was because CTLA-4 controls T cell responses, alongside manipulation of CTLA-4, has become a cornerstone in the development of therapies for autoimmune diseases and cancer." (PMID 36555549, 2022). "There is evidence that many of the susceptibility genes are shared by various autoimmune diseases, such as CTLA4 and PTPN22, which indicate that autoimmune diseases have some similar genetic and molecular pathways." (PMID 34238277, 2021). "Metabolism plays important roles in regulation of other extracellular molecules currently targeted by immune therapy in autoimmune disease in autoimmunity and transplant, including CD40, CD20, CTLA-4, CD25, and CD3." (PMID 34403367, 2021). "Here, we generated a synthetic chimeric peptide comprising the cytoplasmic domain of CTLA‐4 conjugated with the blood brain barrier (BBB)‐permeable peptide dNP2 to stimulate Foxp3 expression in murine and human T cells to treat autoimmune disease." (PMID 34306974, 2021). "The co-stimulatory and co-inhibitory molecules CTLA-4 and ICOS are involved in the pathogenesis of autoimmune disease." (PMID 35222353, 2021). "Since CTLA-4 plays a critical role in MG recovery, it would be a very important strategy to increase CTLA-4 of Treg in the therapy of MG and other autoimmune diseases." (PMID 32148437, 2020). "CTLA‐4 monoclonal antibody has achieved clear efficacy in the treatment of tumors, and it is used as a therapeutic target in research on SAA and other autoimmune diseases." (PMID 32621335, 2020). "Because of the potent inhibition of CTLA-4, a fusion protein composed of the extracellular domain of CTLA-4 and the IgG1 Fc portion (CTLA-4-Ig) was developed and approved to alleviate unwanted immune responses in autoimmune diseases." (PMID 32228715, 2020). "B cells are believed to be important APCs in the pathogenesis of autoimmune diseases and express CD80/CD86 after activation; however, relatively little is known about the effect of CTLA-4-Ig on B cells." (PMID 32228715, 2020). "In the non-pathogenic setting, CTLA-4's constitutive expression on regulatory T cells (T regs) serves a key role in immune tolerance, a regulatory mechanism that prevents the formation of self-reactive T cells that are capable of inducing autoimmune diseases in the host." (PMID 32117295, 2020). "CTLA4-Ig fusion protein (abatacept, an FDA-approved drug for rheumatoid arthritis, an autoimmune disease) is a stable, soluble form of CTLA4." (PMID 28262700, 2017). "Single-nucleotide variants (SNVs) of CTLA-4 gene may represent novel predictive biomarkers in IPI-treated MM patients for their influence on the host immune response through alteration of CTLA-4 expression levels and function in T cells, as shown primarily in autoimmune diseases." (PMID 28446908, 2017).
autoimmune disease (continued). "Given the various molecular mechanisms that have been identified among patients with the same clinical diagnosis, we hypothesize that patient responses to CTLA-4 blockade are more likely to associate with specific molecular alterations rather than the clinically diagnosed autoimmune disease." (PMID 25992290, 2015). "The autoimmune disorders in iR knock-out mice and the IRAE in “checkpoint blockade”-treated patients show that iRs such as PD1 and CTLA-4 are fundamental in the maintenance of a healthy immune homeostasis." (PMID 26167163, 2015). "However, co-inhibitory molecules such as CTLA-4, PD-1 and BTLA have been shown to be crucial for the prevention of autoimmunity and polymorphism or deficiency of these molecules are associated with genetic susceptibility to autoimmune diseases in human and mice." (PMID 23829304, 2013). "Also, CTLA-4 +49 G allele has also been correlated with incomplete glycosylation of the signal peptide and changed processing in the endoplasmic reticulum, which influences the CTLA-4-driven down-regulation of T-cell activation and is of great value in the pathogenesis of autoimmune diseases." (PMID 25013611, 2011). "It is now clear that immune-regulatory genes such as HLA, CTLA-4, and PTPN22 play a major role in the aetiology of HT, GD, and several other autoimmune diseases." (PMID 22654557, 2011). "Additional immune-regulatory loci include MICA/MICB, CTLA4, PTPN22, CIITA, CLEC16A, CD274 (PD-L1), and NLRP1 (NALP1)—variants shared with other autoimmune diseases, underscoring common immune checkpoints rather than AAD-specific genes." (PMID 41465179, 2025). "Blocking CTLA-4 is capable of generating an immune response to cancer and self-tissue, and targeting the CD28/CTLA-4 pathway with antibodies has shown considerable promise in the treatment of cancer and autoimmune diseases." (PMID 39845973, 2024). "Other genes associated with autoimmune disease susceptibility include those involved in immune cell signaling and activation, such as protein tyrosine phosphatase non-receptor type 22 (PTPN22), CTLA-4, and CD40." (PMID 39062908, 2024). "Signals transduced by CTLA-4 following CD80/86 binding, and PD-1 following PD-L1 binding inhibit the “hyperactivation” of T cells and are important in preventing abnormal immune responses commonly seen in autoimmune diseases." (PMID 36969071, 2023). "Unlike PD-1 and CTLA-4, LAG-3 single deficiency was not a factor of autoimmune disease without an autoimmune background and had less antitumor activity." (PMID 37179337, 2023). "The role of CTLA-4 in maintaining tolerance and preventing development of autoimmunity has also been documented in studies where treatment of mice with anti-CTLA-4 monoclonal antibody (mAb) exacerbated autoimmune diseases." (PMID 37342323, 2023). "Data are still needed on the incidence of irAEs in patients with active vs. stable autoimmune disease and on the use of DMARDs (disease-modifying antirheumatic drugs)/steroids at the initiation of ICI therapy and per ICI used (anti-PD1, antiPDL1, anti-CTLA4)." (PMID 35911382, 2022). "The effects of anti-CTLA-4 antibody on CD8+ T, CD4+ T, and Treg cells may contribute to the induction of autoimmune diseases." (PMID 35159059, 2022). "Many of these polymorphisms do not actually change the CTLA-4 amino acid sequence, but can modify the affinity for the CTLA-4 mAb, increasing the risk of occurrence of immunotherapy-induced autoimmune disorders." (PMID 34683167, 2021). "This cell-intrinsic action has been challenged, however, by reports of a mouse model expressing mutant CTLA4 lacking a cytoplasmic tail, which has no lymphocytic infiltrates or autoimmune disease." (PMID 35154081, 2021). "Abatacept, a CTLA-4–Ig fusion protein that blocks the CD28-mediated costimulatory signal necessary for T-cell activation, has been tested in phase I clinical trials for several autoimmune diseases." (PMID 34298735, 2021).
autoimmune disease (continued). "Allelic variation of CTLA4 as well as CTLA4 blockade/anti-CTLA4 treatment influences the signaling threshold of CD4 T-cells, thereby augmenting antitumor immunity but also exacerbating/inducing autoimmune disease." (PMID 32089545, 2021). "It is a known fact that CTLA-4 Ig abatacept blocks CD28-mediated T cell activation by binding to the costimulatory B7 ligands CD80/CD86 on APCs, and it is currently used for RA and other autoimmune diseases." (PMID 32420329, 2020). "None of the macaques treated with CTLA-4 Ab had manifestations of clinical autoimmune disease or any adverse events related to drug or immunization administration during the study." (PMID 32075963, 2020). "At present, some recombinant fusion protein and monoclonal antibodies targeting costimulatory molecules, such as CTLA-4- and LFA-3-Ig, anti-CD3 monoclonal antibody, and so on have been developed and approved to treat autoimmune diseases, such as RA, SLE, IBD, MS, and psoriasis." (PMID 29997500, 2018). "Since CTLA-4 regulates T cell activation and the proliferation through a negative feedback, the CTLA-4 gene is considered to be a candidate gene for T cell-mediated autoimmune disease." (PMID 29850619, 2018). "Programmed death-1 (PD-1) and cytotoxic T-lymphocyte antigen-4 (CTLA-4) expression negatively regulate T cell activity and lack of their expression leads to autoimmune diseases." (PMID 28953925, 2017). "The critical function played by CTLA-4 in regulating Treg function is confirmed by the observation that mice with CTLA-4-lacking Tregs show systemic lympho-proliferation, fatal T cell-mediated autoimmune diseases and potent anti-tumor immunity." (PMID 28404974, 2017). "Notably, augmenting CTLA-4 function by infusing the recombinant soluble form of CTLA-4 called CTLA4-Ig (or abatacept) selectively inhibits T-cell co-stimulation and is beneficial for treating some autoimmune diseases, notably rheumatoid arthritis." (PMID 27487771, 2016). "Although anti-CTLA-4 treatment has been shown to trigger or worsen severity of autoimmune diseases in experimental models, a similar effect has not been shown for PD-1/PD-L1 abrogation." (PMID 26448890, 2015). "The most effective of these has been a soluble form of CTLA-4 (CTLA-4-Ig; Abatacept), which has been FDA approved to treat RA and may be useful in suppressing other autoimmune diseases." (PMID 24586641, 2014). "Cytotoxic T lymphocyte associated antigen-4 [CTLA4; cluster of differentiation (CD152)] is another underlying non-HLA candidate in autoimmune diseases, including MG." (PMID 25003519, 2014). "Third, the gene-specific hypomethylation and noncoding RNAs are also potential mechanisms in many autoimmune diseases such as SLE and RA, suggesting that the epigenetics of CTLA4 might be addressed as well." (PMID 25003519, 2014). "Another explanation is that the set of genes contributing to the establishment of different autoimmune diseases is not the same, and that the CTLA4 gene is important in some diseases but not in others." (PMID 21637411, 2010). "Therefore, SLC5A12 blockade shows multidimensional beneficial effects which are reminiscent of blockade of PD1 and CTLA4 in immuno-oncology, leading us to propose that SLC5A12 represents an important example of a checkpoint in inflamed tissues in autoimmune diseases." (PMID 40759752, 2025). "In addition, it focuses on the different distributions in frequencies of the diverse clinical manifestations due to irAEs between CTLA4 and PD1 pathway inhibitors and the intricate differential with primary autoimmune disorders, which share some pathophysiological and clinical aspects." (PMID 38611115, 2024). "These polymorphisms may not alter the CTLA-4 amino-acid sequence but can affect the affinity for CTLA-4 mAbs, thereby increasing the risk of immunotherapy-induced autoimmune disorders." (PMID 37623461, 2023).